DEFB109D (defensin beta 109D (gene/pseudogene))
Description:
Has antibacterial activity.
Synonyms: DEFB109P3
Gene: Protein-coding gene on chromosome 8 (12,150,888 to 12,158,033, reverse strand). Ensembl gene ENSG00000254866.
Subcellular location: Secreted
Homologues: Orthologues: dog DEFB109B (76% identical), rat Defb42 (66% identical), mouse Defb48 (62% identical). Paralogues in human: DEFB109B (91% identical), DEFB109C (91% identical), DEFB130A (38% identical), DEFB130B (38% identical), DEFB4A (20% identical), DEFB4B (20% identical).